MMP9 (matrix metallopeptidase 9)
Diseases named in the same sentence as MMP9 in open-access papers (continued):
Sharing a sentence is not in itself a finding about the gene and the disease.
cancer (continued). "In cancers, isothiocyanates have been found to downregulate MMP-9 expression and activity." (PMID 29867483, 2018). "In the present study, two kisspeptin phosphinic peptides were designed and synthesized, and their ability to induce phosphorylation of ERK1/2 through kisspeptin receptor and their inhibition on MMP-2 and MMP-9 whose activity correlates with cancer metastasis were assessed." (PMID 29614094, 2018). "Our data also show that MMP2 and MMP9 play a huge role in the migration of cancer cells." (PMID 30241395, 2018). "Furthermore, gelatin zymography showed that MMP-9 activity was upregulated in PTX-treated tumors likely due to the expansion of mesenchymal cancer cell population." (PMID 29507310, 2018). "MMP-9 has been found to be a potential biomarker for several cancers." (PMID 30262739, 2018). "Many published studies have demonstrated that MMP-9 overexpression is associated with various malignant tumours; however, its significance was not clear in other reports." (PMID 30142200, 2018). "Our data provides new information suggesting that AR, EGFR and MMP-9 are interconnected and may play important roles during cancer progression from androgen-dependent state to castration-resistant state." (PMID 30134822, 2018). "Also, MMP-9 promoted growth, infiltration and migration of carcinoma tissues by degrading the basement membrane and extracellular matrix, releasing vascular endothelial growth factors and promoting neonatal angiogenesis." (PMID 29980183, 2018). "In carcinomas, this damage by MMP-9 leads to metastasis and invasion, which are serious challenges." (PMID 30509240, 2018). "In the pathology of the inflammation and the cancer NO· free radicals and MMP-9 are usually higher." (PMID 28969037, 2017). "Therefore, the inhibition of migration mediated by MMP-2 or MMP-9 can putatively provide a preventive measure against cancer metastasis." (PMID 29285298, 2017). "OPN binding to CD44 or integrins has been known to up-regulate the expression or activation of various downstream molecules such as MMP-2, MMP-9, cyclooxygenase-2, and vascular endothelial growth factor, which are essential for determining the oncogenic potential of various cancers." (PMID 29254164, 2017). "The matrix protein FN and the MMP-9 have definite role in cancer cell proliferation and invasion." (PMID 28223935, 2017). "To study whether MGAT5 and MMP9 are required for Barx1-mediated cancer cell invasion and metastasis, we reduced the expression of MGAT5 and MMP9 in SMMC7721-shBarx1 cells with shRNA knockdown." (PMID 29069753, 2017). "MMP-9 is a well-characterized metalloprotease, which is overexpressed in different cancers." (PMID 28931650, 2017). "TIMP-1, TIMP-2, MMP-2 and MMP-9 are cancer metastasis related expressions, Res and PA combination could raise TIMP-1, TIMP-2 and reduce MMP-2 and MMP-9 expressions in HepG2 cancer cells, and these effects were stronger than only PA treatment." (PMID 28978315, 2017). "Since matrix metalloproteinases (MMP) are linked with cancer cell migration and invasion, we performed gelatin zymography to analyze the levels of secreted MMP-2 and MMP-9 following OSU-A9 treatment of BxPC-3 and PANC-1 cells for 24 h and found reduced MMP-2 and MMP-9 proteolytic activity." (PMID 28418923, 2017). "MMP9 overexpression enhances cancer metastasis via breakdown of the extracellular matrix." (PMID 27911270, 2017). "Hence, the high invasive capacity of αvβ6-positive cancer cells is shown by the observation that αvβ6 expression is correlated with an elevated MMP-9 expression at the invasive cancer front." (PMID 28869579, 2017). "In addition, PEITC inhibited invasion of U2OS and SW480 cells was inhibited in a dose-dependent manner, suggesting that the effects of PEITC on the cancer cell invasion are related to regulation of MMP-9 activity." (PMID 28969043, 2017).
cancer (continued). "Furthermore, MMP-2 and MMP-9 can break down collagen, which is an important component of the basement membrane, and are significantly related to cancer invasion and metastasis." (PMID 28152502, 2017). "These marrow-derived cells produce matrix metalloproteinase (MMP)-9, which may promote invasion by cancer cells." (PMID 28545581, 2017). "Moreover, we evaluated the effect of invasiveness on the prognosis of FOXO6 expression in the way of taking MMP-9 as a marker for invasive potential of cancer cells." (PMID 28404958, 2017). "MMP9 is undetectable in healthy tissue, although highly upregulated during inflammation and cancer." (PMID 29212256, 2017). "The significance for most markers in identifying the high-risk cancers was not apparent except with MMP9." (PMID 29254211, 2017). "mTORC1 is related to MMP-2 and MMP-9 activation, contributing to the invasiveness of cancer cells." (PMID 28931650, 2017). "Similarly, an anti-cancer activity of Magnolol has been previously reported, attributed primarily to the Magnolol-dependent reduction in MMP9 expression." (PMID 29259201, 2017). "The results of the present study suggested that cancer-related changes in salivary MMP-9 could be used as a tool for early detection of OSCC." (PMID 28160595, 2017). "RT–PCR analyses revealed lower levels of MMP2, MMP9, and uPA mRNA in daurinol-treated cancer cells." (PMID 28915654, 2017). "In addition, Akt signaling regulates the expression of NF-κB as well as MMP-9 in several cancer cells." (PMID 28288190, 2017). "We also hypothesize that MMP9 (be epithelial-derived or neutrophil-derived) will always be a mediator of acute inflammation and sporadic cancers." (PMID 27861153, 2017). "MMP9, FN1, FGF13, and COL4A2 are significant genes in the pathways associated with cancer." (PMID 28191466, 2017). "We also found that BsAb can reduce the expression of proliferation, angiogenesis, migration, and invasion-related proteins, including Ki-67, VEGF-A, and MMP-9, which indicates its potent ability to inhibit cancer cell proliferation, angiogenesis, migration, and invasion in vivo." (PMID 28404966, 2017). "Secondly, the expression of MMP-2 and MMP-9 can also be regulated by ERK1/2 in cancer cells." (PMID 28424406, 2017). "The inhibition of MMP-2 and MMP-9 enzyme activities can prevent of cancer metastasis." (PMID 29285298, 2017). "The high levels of MMP2 and MMP9, which are important factors in extracellular matrix remodeling, are evidence of good biomimicry, and we can conclude that the fibroblast-layered microtissue better represents cancer tissues than the monocultured microtissue." (PMID 29112150, 2017). "Both NGAL and MMP-9 proteins may be useful in assessing the stage of the cancer, before surgical treatment." (PMID 29089666, 2017). "The importance of Casp12 in hardwiring NF-κB signal transduction pathways to the regulation of MMP-9 gene may be a therapeutic target for carcinoma." (PMID 28380444, 2017). "All these observations suggested the rational to study MMP-9 in cancer." (PMID 27115178, 2016). "The proteases MMP-2 and MMP-9 are known to favor the migration and invasion of cancer cells." (PMID 27282478, 2016). "It facilitates the invasion and metastasis of cancer cells by promoting matrix metalloproteinase-9 (MMP-9) secretion and by inducing the epithelial mesenchymal transition (EMT) while it also increases telomerase activity and replication by activating telomerase reverse transcriptase (TERT)." (PMID 27418953, 2016). "The abnormal expression of MMP-9, occurring in cancer cells, may be sustained by hypomethylation or genomic alterations of its promoter." (PMID 27115178, 2016). "Similarly, miR-29, miR-218, miR-340 and miR206 were reported to regulate MMP2 and MMP9 and these effects were also profound in cancer cells." (PMID 27992561, 2016). "Moreover, the ability of serum MMP-9 (AUC: 0.67; P < 0.05) and IL-8 (AUC: 0.72; P < 0.005) to diagnose cancer (from HD) were found to be significant." (PMID 27811960, 2016).
cancer (continued). "Furthermore, EBV-miR-BART6-3p mimics inhibited metastasis and invasion-related genes, including MMP2 and MMP9 in three EBV-negative cancer cell lines." (PMID 27584792, 2016). "Other than STAT-3, NF-κB also plays a vital role in development and metastasis of cancer and regulates expression of many genes including MMP-9 and FAK; hence we hypothesized that NF-κB pathway would as well be impacted by OV." (PMID 27242913, 2016). "B7-H3 had a close relationship with the T stage of cancer and was co-expressed with MMP2 and MMP9 in cancer tissues, which might originate from its ability to promote the EMT." (PMID 27145365, 2016). "In addition to cancer-promoting inflammatory mediators, TAMs secrete MMPs including MMP9 to promote metastasis." (PMID 27487154, 2016). "In addition, Akt and other MAPK pathways are also reported to be coupled to MMP-2 and MMP-9 expression and play essential roles during cancer progression." (PMID 27057634, 2016). "We speculate that this is done via the downregulation of the intrinsic or radiation-enhanced MMP-9 expression by AEG-1 in the cancer cells." (PMID 27835571, 2016). "Notably, MMPs [such as MMP-2 (gelatinase A) and MMP-9 (gelatinase B)] have been reported to degrade type IV collagen to facilitate cancer cell invasion and metastasis." (PMID 27349797, 2016). "It has been reported that MMP9 is also involved in cancer cell migration." (PMID 26906973, 2016). "MMP9 levels are functionally related to the metastasis and invasion properties of cancer cells." (PMID 27811013, 2016). "Furthermore, among these miRNAs we identified which of them are able to interact with a wide range of genes involved in EMT and NGAL/MMP-9 pathways but also in many other different cancer pathways." (PMID 27602581, 2016). "We speculate that TM4SF1-mediated upregulation of uPA, MMP-2, and MMP-9 increases the degradation of ECM by cancer cells, leading to invasion and metastasis of cancer cells." (PMID 27153056, 2016). "MMP-9 has been previously reported to promote the metastasis of cancer cells." (PMID 27999314, 2016). "Both HDAC5 and HDAC6 could influence the metastasis of A375 cells by regulating MMP9 and vimentin, both markers for the metastasis ability of cancer cells." (PMID 26747087, 2016). "Importantly, the introduction of MMP-9 expressing bone marrow cells induced proliferation and neoplastic progression, indicating a crucial role for immune cells in MMP-9 driven cancer progression." (PMID 27888810, 2016). "Literature review expresses that overexpression and hyperactivity of MMP-2 and MMP-9 has been observed in pre-cancer and cancer lesions of all kinds of cancers including the uterine cervical cancer which is second most common malignant tumor among female in the developing countries." (PMID 27659937, 2016). "Moreover, OV suppressed cell invasiveness and interfered with cell-matrix adhesion in Mia-PaCa2 cancer cells by reducing MMP-9 and FAK transcription through suppressing NF-κB and STAT3 pathway." (PMID 27242913, 2016). "N-cadherin may have contributed to the invasive characteristics of carcinoma cells by upregulating MMP-9 in response to MAPK or NF-κB signaling, thereby increasing the aggressive metastasis." (PMID 27737648, 2016). "N-cadherin might contribute to the invasive characteristics of carcinoma cells by upregulating MMP-9, thereby leading to increased aggressive metastasis." (PMID 27737648, 2016). "The increase in circulating levels of MMP-9 and ET-1 could be a possible linkage between MetS and cancers." (PMID 26692905, 2015). "Both MMP3 from LC cells and MMP9 from TAM enhance cancer metastasis." (PMID 25961789, 2015). "Here, we report that EGF and BMP-4 cooperate to inhibit MMP-9 expression in cancer cells." (PMID 25897433, 2015). "MMP9, which can degrade collagen IV, plays an important role in cancer metastasis." (PMID 25638174, 2015).
cancer (continued). "Of the MMPs, MMP-2, MMP-9, and their upstream enzyme, urokinase-PA (u-PA), are the most vital enzymes for degrading the main constituent of the basement membrane, type IV collagen, and are deeply involved in cancer invasion and metastasis." (PMID 25605016, 2015). "The OPN/MMP-9 pathway represents a new molecular mechanism involved in cancer metastasis." (PMID 26289107, 2015). "Decorin reportedly augments the expression of MMP-9 in cancer cell lines." (PMID 25781946, 2015). "We also observed down-regulation of MMP-9, which is considered crucial for cancer cell invasion." (PMID 25923701, 2015). "Consequently, a large number of studies have focused their attention on identifying and characterizing the molecular mechanisms that are responsible for increased expression of MMP-9 in cancer." (PMID 25897433, 2015). "NF-κB is a sequence specific transcription factor that regulates expression of many cellular genes such as genes involved in cancer cell survival (Mcl-1), proliferation (C-myc, Cyclin D1), and invasion (matrix metalloproteinase MMP-9), which play important roles in carcinogenesis." (PMID 25875501, 2015). "NF-κB plays an important role in regulating MMP-9 expression in various cancer cell lines." (PMID 25670016, 2015). "Exogenous MMP9 can rescue the invasion ability of cancer cells that treated with PMS." (PMID 26674531, 2015). "Furthermore, increasing evidence demonstrate that several MMPs (including MMP-9) expression and activation were regulated by NF-κB activation in many human cancers." (PMID 25888829, 2015). "Recently, we reported the potential use of star-shaped copolymers to co-deliver docetaxel and MMP-9 siRNA plasmids in cancer therapy; thus, demethylation drugs in combination with such copolymers may increase the specificity of targeted therapy in the future." (PMID 26509736, 2015). "Furthermore, increasing evidence demonstrate that MMP-9 expression and activation were regulated by p65 up-regulation and nuclear translocation which induced NF-κB activation in many human cancers." (PMID 25888829, 2015). "Thus, MMP-9 is an attractive target to decrease the invasiveness and metastasis of cancers that overexpress this protein." (PMID 25670016, 2015). "Furthermore, PI3K/AKT contributes to extracellular matrix destruction by increasing the production of MMP-2 and MMP-9 in many cancers." (PMID 25927939, 2015). "Polymorphisms in promoter regions of MMP genes might be related to the susceptibility of digestive cancers, with a role in cancer development for MMP1 and MMP7, and a role of protection against cancer for MMP2 and MMP9." (PMID 25596746, 2015). "MMP2 and MMP9 contain fibronectin repeats that help them recognize gelatin (denatured collagen) as a substrate and Type IV collagen is the main constituent of the BM, one of the first barriers that cancer cells need to traverse to metastasize." (PMID 25699257, 2015). "Thus, agents and/or natural plant products that inhibit both MMP-9 expression and activity have received considerable attention for their potential use in the treatment of malignant and invasive cancers." (PMID 25670016, 2015). "Additionally, cancer cells have lesser capability to colonize the lungs of MMP2 or MMP9 deficient mice compared to wild type mice and cancer cell proliferation is decreased in tumors obtained from MMP9 knock-out mice." (PMID 25699257, 2015). "Additionally, cancer metastasis is inhibited by the inhibition of MMP-9 through blocking mTOR signaling." (PMID 26202311, 2015). "As MMP2 and MMP9 were crucial proteins involved in cancer cell metastasis, we reasoned that SAE2 might regulate MMP expression in the SCLC." (PMID 26063074, 2015). "In summary, ARs are associated with local cancer cell infiltration, in which MMP-2 and MMP-9 may play important roles in the HCC microenvironment to increase invasion and metastasis." (PMID 25667651, 2015). "MMP-9 has also been shown to be involved in angiogenesis and metastasis of certain cancers." (PMID 26692905, 2015).
cancer (continued). "MMP-2 and MMP-9 have important roles in the invasion of cancer cells." (PMID 25633440, 2015). "Inhibition of MMP-2 and MMP-9 activity can suppress cancer metastasis." (PMID 26304749, 2015). "Matrix metalloproteinase-9 (MMP-9) plays a central role in the progression of the cancer." (PMID 25897433, 2015). "AP-1 is a major transcription factor that regulates MMP-9 expression, which may contribute to the lower invasiveness and growth potential of cancer cells." (PMID 25760437, 2015). "MMP9 is known to contribute to metastasis, and can be secreted by both cancer cells and BMDCs." (PMID 26497998, 2015). "Moreover, NF-κB expression in the nucleus contributes to the activation of MMP-2 and MMP-9, which play critical roles in cancer metastasis." (PMID 25394920, 2015). "MMP-2 and MMP-9, two major MMPs, play important roles in cancer cell invasion and metastasis 35,36." (PMID 25753200, 2015). "We then examined the influence of EGF on MMP9 transcription as well as on the transcription of additional MMPs (MMP-1, MMP-2, MMP-3, MMP-7, MMP-10, MMP-13, MMP14, MMP15) and of CD44, a cell adhesion glycoprotein implicated in EMT and cancer metastasis." (PMID 26084289, 2015). "To determine whether MMP-9 expression is regulated by OPN in a signaling pathway similar to that observed in cancer cells, we used siRNA interference to downregulate OPN." (PMID 26289107, 2015). "Meanwhile, Slug could also cooperate with Snail or other transcription factors to maintain longer-term EMT in cancer cells, by upregulating MMP-9 expression." (PMID 25879017, 2015). "MMP7 and MMP9 are expressed in cancer cells that invade nervous tissue." (PMID 26576639, 2015). "Moreover, the failure of broad-spectrum MMP inhibitors in clinical trials of cancer treatment has led to the development of selective MMP inhibitors, and inhibitors that target MMP-9 have been indicated as potential treatments for cancer." (PMID 26230665, 2015). "The angiogenic effect of MMP-9 has been reported in several cancer models." (PMID 26819959, 2015). "Matrix metalloproteinase-9 (MMP-9), also known as the largest gelatinase in the family of matrix metalloproteinases, is a zinc-dependent endopeptidase that facilitates the degradation of type IV collagen in many cancers." (PMID 26289107, 2015). "Therefore, inhibition of MMP-2 and MMP-9 expression should be a high priority during cancer therapy." (PMID 26098839, 2015). "Various MMPs, e.g. MMP9, are expressed in carcinomas, correlating with local invasion." (PMID 25623198, 2015). "MMP-2 and MMP-9 are key factors in cancer cell invasion and metastasis in vitro." (PMID 24520272, 2014). "In our study, we sought to determine whether MMP-2 and/or MMP-9 expression differed between aggressive cancers on the positive margin of the resection that progress and cancers that remain localized." (PMID 25097794, 2014). "Since cancer stem and normal stem cells share molecular machinery and cancer stem cells hijack physiological stem cell trafficking mechanisms, gelatinase B/MMP-9 is likely to play a similar role in stimulating the proliferation cancer stem cells that locate to the bone metastatic niche." (PMID 24473089, 2014). "One possible mechanism through which KY-05009 inhibits invasion could be through its attenuation of TGF-β1-induced expression and activation of MMP-2 and MMP-9 via NF-κB, which is a well-known transcription factor that controls cancer metastasis." (PMID 25337707, 2014). "Our RNA-Seq data shows that expression of FN1, MSN and MMP9, which belongs to “Proteoglycans in cancer” gene list and are targets of down-regulated miRNAs, was up-regulated in 10 of 13 tissue samples (on average, 6.83, 2.43 and 21.89 folds, respectively, compared to adjacent normal)." (PMID 25126847, 2014). "A few studies suggested that the complex could increase pro-MMP-9’s enzyme activity via an autocatalytic process thus favoring the invasion of cancer cells through the basement membrane." (PMID 24713998, 2014).